LINC00588 (long independently transcribed non-coding RNA 588)
Synonyms: DKFZP434F122; formerly C8orf71
Gene: Long non-coding RNA gene on chromosome 8 (57,279,543 to 57,286,968, forward strand). Ensembl gene ENSG00000215117.
Diseases named in the same sentence as LINC00588 in open-access papers:
LINC00588 is named in the same sentence as 1 disease in open-access papers, as found by Europe PMC text mining. Sharing a sentence is not in itself a finding about the gene and the disease. The quoted sentences say what the papers report.
tumor (1 paper, 2020). "LINC00588 knockdown significantly increased the tumor volume and weight in U20S cell lines compared with control groups, while the overexpression of LINC00588 could reduce the tumor volume and weight of U20S cell lines compared with control groups." (PMID 32265694, 2020). "Overexpression of LINC00588 appeared to inhibit cell proliferation, viability, migration, invasion, endothelial cell function, EMT, and tumor growth but not apoptosis, while we got the opposite result when we knocked down LINC00588." (PMID 32265694, 2020).